FOXL2 (forkhead box L2)
Diseases named in the same sentence as FOXL2 in open-access papers (continued):
Sharing a sentence is not in itself a finding about the gene and the disease.
endometrial cancer (3 papers, 2020 to 2022). Primary or metastatic malignant neoplasm involving the endometrium (mucous membrane that lines the endometrial cavity). "A bioinformatics study of endometrial cancer indicated that the down-regulation of Forkhead Box L2 (FOXL2) in endometrial cancer tissues or cells is associated with cell growth." (PMID 33671587, 2021). "In this study, we observed that FOXL2 was down-regulated in endometrial cancer tissues and was significantly associated with endometrial cancer." (PMID 32555395, 2020). "More importantly, FOXL2, a down-regulated key gene in endometrial cancer, is regulated by miR-34c-5p." (PMID 35154016, 2022). "In summary, four core genes (TOP2A, ASPM, EFEMP1 and FOXL2) and several interesting pathways involved in endometrial cancer were identified." (PMID 32555395, 2020). "Although many RNA-sequencing studies have been performed to understand the genetic regulation of endometrial cancer, the relationship between FOXL2 and the disease is still lacking." (PMID 32555395, 2020). "In the current study, analysis on GSE115810 showed that FOXL2 was one of the top10 DEGs found to be down-regulated during the development of endometrial cancer." (PMID 32555395, 2020). "On the other hand, we observed a significantly low FOXL2 expression in endometrial cancer relative to normal cells." (PMID 32555395, 2020). "Meanwhile, we observed a down-regulation of FOXL2 in endometrial cancer cells while the expression of miR-133a, which targets FOXL254, was high in the cancerous cells." (PMID 32555395, 2020). "Aberrant expression levels of four genes out of 12 core DEGs showed a significant (P < 0.05)association with poor prognosis of endometrial cancer, and this included two up-regulated (TOP2A and ASPM) and two down-regulated (FOXL2 and EFEMP1) genes." (PMID 32555395, 2020). "When this study isolated exosomes from the supernatants of endometrial cancer cell lines, it was indicated that miR-133a targeting FOXL2 could be delivered to normal endometrial cells by exosomes." (PMID 33671587, 2021). "Furthermore, a cross comparison of common DEGs across the three datasets revealed that TOP2A, ASPM, FOXL2 and EFEMP1 were potential biomarkers for distinguishing endometrial cancer, and this was significantly associated with the survival ratios among patients." (PMID 32555395, 2020). "Finally, we performed a survival analysis and identified four genes (TOP2A, ASPM, EFEMP1, and FOXL2) that play key roles in endometrial cancer." (PMID 32555395, 2020). "In addition, exosomes secreted by endometrial cancer cells, contain miRNAs that regulate FOXL2 and can be transported to normal stromal cells." (PMID 32555395, 2020). "Results showed a significant down-regulation of EFEMP1 and FOXL2 in endometrial cancer cells." (PMID 32555395, 2020). "Exosomal miR-133a may regulate the down-regulation of FOXL2 in endometrial cancer tissues." (PMID 32555395, 2020). "We found up-regulation of TOP2A and ASPM in endometrial cancer tissues or cells, while EFEMP1 and FOXL2 were down-regulated." (PMID 32555395, 2020). "Analysis of qRT-PCR assay revealed that expression of mRNA for TOP2A and ASPM are up-regulated in endometrial cancer cells, whereas those of EFEMP1 and FOXL2 are down-regulated." (PMID 32555395, 2020). "Further validation in endometrial cancer cells showed that indeed TOP2A, ASPM, FOXL2 and EFEMP1 were significantly regulated." (PMID 32555395, 2020). "On the other hand, HAND2-AS1, PEG3, OGN, SFRP4, WT1, FOXL2 and EFEMP1 were significantly lower in endometrial cancer tissues than in normal tissues." (PMID 32555395, 2020). "Currently, there are no studies on the role of ASPM and FOXL2 in endometrial cancer." (PMID 32555395, 2020). "Furthermore, we isolated exosomes from the culturing supernatants of endometrial cancer cells (Ishikawa and HEC-1-A) and found that miR-133a, which regulates expression of FOXL2, were present in exosomes and that they could be delivered to normal endometrial cells." (PMID 32555395, 2020).
Eyelid malformation (3 papers, 2009 to 2021). "This might be due to the fact that the targets of FOXL2 (with respect to eyelid malformations) may be much more than OSR2." (PMID 33796131, 2021).
ovarian disease (3 papers, 2020 to 2023). "While the mechanism by which the FOXL2 misregulations induce such ovarian diseases has been actively investigated, the mechanisms underlying the regulation of FOXL2 expression are not known." (PMID 36424497, 2022).
Premature ovarian insufficiency (3 papers, 2018 to 2019). Amenorrhea due to loss of ovarian function before the age of 40. "FOXL2 gene mutations cause blepharophimosis-ptosis-epicanthus inversus syndrome (BPES) and may be associated with premature ovarian insufficiency (POI)." (PMID 31366388, 2019).
Turner syndrome (3 papers, 2017 to 2024). Turner syndrome is a chromosomal disorder associated with the complete or partial absence of an X chromosome. "When this is the case, the underlying pathogenetic mechanism of follicle depletion are heterogeneous ranging from genetic (Turner’s syndrome, mutations in the genes FMR-1, BMP-15, Foxl2, and recently identified MCM9, SYCE1, STAG3) to auto-immune and iatrogenic causes." (PMID 29176793, 2017). "When attempting to replicate the differentiation process of embryonic granulosa cells, we observed the downregulation of specific genes—GATA4, FOXL2, AMHR2, CYP19A1, and FSH—in Turner syndrome-derived granulosa cells (TS-GCs)." (PMID 39543104, 2024).
adenomyosis (2 papers, 2022 to 2024). The growth of endometrial tissue inside the muscular wall of the uterine corpus. "The protein levels of all these factors were lower in adenomyosis mice compared with control (FOXL2, P = 0.0499; FSHR, P = 0.0044; BMP15, P = 0.0207)." (PMID 38451875, 2024). "Deregulated Wnt signaling pathways play a crucial role in the development of adenomyosis in the Foxl2 deleted mice, and constitutive activation of β-catenin in the murine uterine horns can also lead to the development of adenomyosis through promoting EMT in the epithelial cells." (PMID 35330066, 2022). "To further investigate how folliculogenesis was impaired in mice affected by adenomyosis, we performed western blot analysis to evaluate the expression of three crucial oocyte-derived factors involved in follicular development: BMP15, FOXL2, and FSHR." (PMID 38451875, 2024). "The reduced expression of critical oocyte-derived factors, including Foxl2, BMP15, and FSHR, further indicates ovarian dysfunction in adenomyosis." (PMID 38451875, 2024). "However, since so far there has been no report on the association between adenomyosis and genetic mutations or polymorphisms on either Dicer, Wnt, β-catenin, or Foxl2, the utility of these models in elucidating the pathogenesis of adenomyosis appears to be limited." (PMID 35330066, 2022). "Adenomyosis has also been found in the uterine horns of some transgenic mice, such as Dicer inactivated mutant mice, follicular stimulating hormone (FSH) receptor (FSHR)-haplo-insufficient mice, Foxl2 deleted mice, and mice with impaired prostaglandin D2 (PGD2) synthesis." (PMID 35330066, 2022).
amblyopia (2 papers, 2011 to 2018). Decreased vision that results from abnormal visual development. "For example, a heterozygous FOXL2 missense mutation c.C650G (p.S217C) identified in an Iranian family with BPES gives rise to a striking phenotype with bilateral amblyopia." (PMID 30029625, 2018).
autoimmune disorders (2 papers, 2022 to 2026). "The persistence of follicular defects, including reduced AMH and FOXL2 levels, in DM ovaries even in severe combined immunodeficient mice reveals that POI is not due to autoimmunity and the phenotype results from intrinsic defects in follicular development caused by the oocyte-specific mutation." (PMID 41865494, 2026).
germ cell tumor (2 papers, 2015 to 2019). A benign or malignant, gonadal or extragonadal neoplasm that originates from germ cells. "Gonadal biopsy and immunohistochemical biomarkers (OCT3/4 (POU5F1), TSPY, SOX9, FOXL2 and KITLG (SCF)) are important to characterize situations in which GCC development is possible (germ cells tumors)." (PMID 31721911, 2019). "Newer markers for the sex cord stromal family of tumors include SF-1 and FOXL2, which are highly specific and are not expressed by germ cell tumors." (PMID 26742984, 2015).
hypogonadism (2 papers, 2014 to 2024). A disorder characterized by decreased function of the gonads. "Deletion of the Type II activin receptor as well as gonadotrope-specific knockdown of both SMAD4 and FOXL2 resulted in a hypogonadal hypogonadism phenotype reminiscent of the Fshb knockout." (PMID 25423188, 2014).
keloid (2 papers, 2013 to 2025). An irregularly shaped, elevated mark on the skin caused by deposits of excessive amounts of collagen during wound healing. "At 3p22.3, the SNPs rs940187 and rs1511412 within FOXL2 were significant associated with keloid in Japanese population (P = 1.80×10−13, OR = 1.98, and P = 2.31×10−13, OR = 1.87, respectively)." (PMID 23667473, 2013). "The heatmap illustrates the differential expression of these 13 OSRDEGs between keloid and normal skin tissues, where F3, FOXL2, EDN1, and NTF3 show higher expression in keloid tissues, while BDNF, FLT1, VCAM1 and ADRB2 are more highly expressed in normal skin." (PMID 40051702, 2025).
liver cancer (2 papers, 2017 to 2024). An epithelial or non-epithelial malignant neoplasm that arises from the liver. "These experimental results not only support the notion that FOXL2 is a potential biomarker for liver cancer treatment but also provide significant molecular evidence for the development of new therapeutic strategies." (PMID 39764438, 2024). "In our drug sensitivity analysis, we identified a significant positive correlation between FOXL2 and Lenvatinib, suggesting that FOXL2 may serve as a potential biomarker for liver cancer therapy." (PMID 39764438, 2024). "The drug sensitivity correlation and molecular docking results of FOXL2 with the liver cancer-targeting agent lenvatinib emphasized its potential role in hepatocellular carcinoma treatment and highlighted the importance of FOXL2 in hepatocellular carcinoma treatment." (PMID 39764438, 2024). "Furthermore, this paper identifies FOXL2 as a promising liver cancer marker through gene ontology and survival analysis." (PMID 39764438, 2024).
promyelocytic leukaemia (2 papers, 2010 to 2011). "Interestingly, FOXL2 SUMOylation promotes its transient recruitment to subnuclear structures that we demonstrate to be PML (Promyelocytic Leukemia) Nuclear Bodies." (PMID 22022399, 2011). "When FOXL2 was co-transfected with SUMO-1 in COS-7 cells, co-localization was observed by confocal microscopy in structures reminiscent of PML (promyelocytic leukaemia) bodies." (PMID 20209145, 2010).
squamous cell carcinoma (2 papers, 2017). A carcinoma arising from squamous epithelial cells. "Another notable finding was that 21 of 25 samples (84%) with FOXL2 amplification-dependent overexpression were derived from squamous cell carcinoma of the lung (10 of 56), head and neck (9 of 101), and esophagus (2 of 14), and its frequency was 12% of a total of 176 squamous cell carcinoma samples." (PMID 28377632, 2017).
adenoma (1 paper, 2023). A neoplasm arising from the epithelium. "The resultant data analyses of the folliculogenesis genes revealed that Lhr and Ahr mRNA in the sex cord and adenoma phenotype, and Foxl2 and Bmpr2 mRNA in tubulostromal adenomas, were similarly expressed to that in mature GCs, with levels significantly different to the naïve cells." (PMID 37174061, 2023).
adrenocortical cancers (1 paper, 2017). "However, more studies are needed to expand our understanding of how JDP2 coordinates with NR5A1 and FOXL2 to influence MC2R activity in adrenal glands and adrenocortical cancers." (PMID 28146118, 2017).
Anisometropia (1 paper, 2023). Inequality of refractive power of the two eyes. "In conclusion, this study revealed variant c.672_701dup in FOXL2 as a BPES-causing variant in a family with the rare features of anisometropia, unilateral PM and/or congenital cataracts, thus expanding the phenotypic spectrum of FOXL2." (PMID 37932670, 2023). "This study uncovered the variant c.672_701dup in FOXL2 as a disease causal variant in a rare-presenting BPES family with anisometropia, unilateral pathogenic myopia, and/or congenital cataracts, thus expanding the phenotypic spectrum of FOXL2." (PMID 37932670, 2023). "This study confirmed a non-frameshift variant c.672_701dup (p.A225_A234dup) in FOXL2 as a disease-causing variant associated with a rare BPES pedigree that presents with anisometropia and unilateral PM." (PMID 37932670, 2023).
cervical squamous cancer (1 paper, 2020). "A related study showed that that FOXL2 could suppress cells proliferation and enhance cells apoptosis in cervical squamous cancer, mainly by decreasing Ki67 expression." (PMID 32555395, 2020).
cyst (1 paper, 2018). A sac-like closed membranous structure that may be empty or contain fluid or amorphous material. "We showed that FOXL2-poor cases had a significantly larger number of plasma cells in the areas distant from cancer cells such as tumor capsules or neighboring cyst walls, when compared with FOXL2-rich cases." (PMID 30304016, 2018).
developmental delay (1 paper, 2009). "This suggests that Foxl2+/- heterozygous ovaries undergo a developmental delay starting in fetal life." (PMID 19538736, 2009).
dysgerminoma (1 paper, 2022). A malignant germ cell tumor characterized by the presence of a monotonous primitive germ cell population. "The definitive diagnosis of GCNIS/GB, dysgerminoma, or other gonadal neoplasms was confirmed with histopathological features and immunohistochemical stains of markers like PLAP, SALL4, OCT3/4, TSPY, and FOXL2." (PMID 35935368, 2022).
endometrial stromal sarcoma (1 paper, 2025).
endometrioid carcinoma (1 paper, 2018). "In a few cases of endometrioid carcinoma (5 out of 21) and serous carcinoma (2 out 21), a small number of FOXL2-positive stromal cells were detected." (PMID 30304016, 2018).
gonadoblastoma (1 paper, 2015). A mixed germ cell/sex cord-stromal tumor characterized by the presence of large germ cells which resemble seminoma cells and small cells which resemble Sertoli or granulosa cells. "Unexpectedly, our case showed co-expression of SOX9 and FOXL2 in abnormally shaped seminiferous tubules and gonadoblastomas." (PMID 25860218, 2015). "As for gonadoblastoma, co-expression of SOX9 and FOXL2 was observed only in a minority of sex cord cells with 45,X." (PMID 25860218, 2015).
granulosa-cell tumor of the testis (1 paper, 2009). "This was the first association of a somatic mutation in FOXL2 associated with cancer, however aberrant expression of Foxl2 has been reported in juvenile granulosa-cell tumor of the testis." (PMID 19956657, 2009).
hepatocellular carcinoma (1 paper, 2024). A malignant tumor that arises from hepatocytes. "Validation using box plots showed that the expression of the gene FOXL2 was higher in patients with hepatocellular carcinoma than in normal individuals." (PMID 39764438, 2024).
Hirsutism (1 paper, 2016). Abnormally increased hair growth referring to a male pattern of body hair (androgenic hair). "Moreover, androgen-induced hirsutism, described in patients with PCOS, is also observed in women carrying FOXL-2 mutations." (PMID 27102646, 2016).
insulinomas (1 paper, 2021). "Copy number alterations involving FOXL2, IRS2, CEBPA and ATRX genes were observed in insulinoma as well as in micro-tumors samples, suggesting that alterations of these genes may promote malignization in the β-cells population." (PMID 34737724, 2021). "In our studied samples of micro-tumors, we have not found alteration in MEN1, but gain status in IRS2, FOXL2 and CEBPA genes was found, suggesting that they can play a role in the development of micro- to macro-tumors, to wit insulinomas, and, accordingly, insulinomatosis." (PMID 34737724, 2021).
Leydig cell tumor (1 paper, 2023). A sex cord-stromal tumor occurring in the testis and rarely in the ovary. "Leydig cells have the same immunoprofile than those of Leydig cell tumors (calretinin+, inhibin+, FOXL2-; see Section 3.2.1." (PMID 38136408, 2023). "The immunoprofile is identical to that of Leydig cell tumors with positive expression of inhibin, calretinin, MelanA, CD99, and with FOXL2 and EMA negativity." (PMID 38136408, 2023).
mantle cell lymphoma (1 paper, 2023). Mantle cell lymphoma is a rare form of malignant non-Hodgkin lymphoma affecting B lymphocytes in the lymph nodes in a region called the ``mantle zone''. "For example, FOXC1 and FOXL2, which are mutated in people affected by Dandy-Walker and regulate cerebellum development, are hypermethylated in mantle cell lymphomas with increased levels of G9A." (PMID 37470706, 2023).
microcephaly (1 paper, 2008). A congenital or acquired developmental disorder in which the circumference of the head is smaller than normal for the person's age and sex. "In a review of the literature, de Ru and colleagues noted that most of the BPES patients with a cytologically detectable deletion or a microdeletion on chromosome 3q, where FOXL2 resides, also exhibited microcephaly and short stature." (PMID 19440510, 2008).
non-small cell lung carcinoma (1 paper, 2023). A group of at least three distinct histological types of lung cancer, including non-small cell squamous cell carcinoma, adenocarcinoma, and large cell carcinoma. "Forkhead box L2 (FOXL2) has been recognized as a transcription factor in the progression of many malignancies, but its role in non‐small cell lung cancer (NSCLC) remains unclear." (PMID 36846934, 2023).
Palmoplantar hyperkeratosis (1 paper, 2008). Abnormal thickening of the skin localized to the palm of the hand and the sole of the foot. "Intriguingly, both RSPO1, FOXL2 and PIS mutations are also associated with failure of epithelium differentiation at different specific position, palmoplantar hyperkeratosis in RSPO1-/- patients, eyelids malformation in FOXL2+/- patients and hornless in PIS-/- goats." (PMID 18384673, 2008).
pancreatic cancer (1 paper, 2015). "Chromosome Conformation Capture related techniques have already been successfully applied to uncover interactions between distant regulatory elements, as occurs with CDKN2B in pancreatic cancer susceptibility or FOXL2 gene in blepharophimosis syndrome." (PMID 25701871, 2015).
pituitary adenomas (1 paper, 2011). "As distribution of FOXL2 appeared to mirror clusterin expression in pituitary adenomas, we tested whether FOXL2 stimulates clusterin in gonadotroph cells." (PMID 21464964, 2011).
Primary amenorrhea (1 paper, 2021). "The 19-year-old patient suffered from primary amenorrhea with underlying low AMH and abnormal ovarian histology (polyovular follicles, defective basal lamina, deposition of cholesterol crystals, advanced expression of proliferative marker Ki67, and intracytoplasmic FOXL2 aggregation)." (PMID 34711234, 2021).
serous carcinoma (1 paper, 2018). "We found only four exceptional cases of serous carcinoma that contained a small number of FOXL2-positive cells at peritoneal seeding sites." (PMID 30304016, 2018). "However, in a few cases of peritoneal metastases of serous carcinoma (4 out of 15), a small portion (less than 5%) of fibroblast-like spindle cells showed FOXL2 positivity." (PMID 30304016, 2018). "In contrast, only a few FOXL2-positive cells were found in peritoneal seeding sites of four serous carcinoma cases, and all the other tumors at extraovarian sites had no FOXL2-positive cells." (PMID 30304016, 2018).